ENSG00000302384 (novel transcript)
Gene: Long non-coding RNA gene on chromosome 16 (3,152,896 to 3,153,135, forward strand). Ensembl gene ENSG00000302384.
Gene Ontology:
Molecular function: triplet codon-amino acid adaptor activity
Biological process: translation